INS (insulin)
Diseases named in the same sentence as INS in open-access papers (continued):
Sharing a sentence is not in itself a finding about the gene and the disease.
diabetes (continued). "The 2025 American Diabetes Association Standards of Care in Diabetes recommend quarterly hemoglobin A1c (HbA1c) testing, in addition to blood glucose monitoring and continuous glucose monitoring (CGM) for people who are treated with any type of insulin therapy." (PMID 40532195, 2025). "Moreover, PGC‐1α accumulation may be beneficial for treating atrophy in diabetes by improving insulin sensitivity in insulin‐resistant skeletal muscles and enhancing glucose homeostasis and insulin secretion from pancreatic B cells." (PMID 40875495, 2025). "Studies have established a connection between diabetes mellitus and thyroid disorders, indicating that diabetes related traits such as elevated insulin levels, insulin resistance, metabolic dysregulation, and oxidative stress may exacerbate the severity of thyroid conditions." (PMID 40927522, 2025). "Phenotypic differences can be observed between diabetic cardiomyopathy in type 1 and type 2 diabetes mellitus and between the basis for mitochondrial dysfunction in insulin-responsive type 1 versus insulin-resistant type 2 diabetic hearts, possibly due to different myocardial insulin action." (PMID 40161891, 2025). "Moreover, AMPK activators like metformin have shown efficacy in improving insulin sensitivity and reducing hyperglycemia in diabetes, including GDM, and may also benefit placental energy metabolism by enhancing glycolytic flux and glucose uptake." (PMID 40136665, 2025). "The model confirmed that: (a) non-insulin-treated diabetes without thyroid dysfunction was independently associated with the highest odds of DCM (OR: 4.27, 95% CI: 2.63–6.94, p < 0.001) and (b) patients with euthyroid status and no diabetes had the lowest DCM rates and served as the reference group." (PMID 41153651, 2025). "In addition, incorporating clinical characteristics such as insulin therapy, long diabetes duration, and obesity into disaster response protocols could enable targeted monitoring and prioritization of high-risk individuals." (PMID 41008733, 2025). "Additionally, increasing functional muscle mass (assuming it is possible) would be beneficial for treating diabetes, as a loss of skeletal muscle mass is frequently associated with both T1DM and T2DM due to catabolism caused by malfunction of insulin-related issues." (PMID 39340593, 2025). "In a sensitivity analysis using mixed-effects logistic regression with a random intercept for center, results were unchanged: procedure type remained non-significant at both 1 and 2 years, whereas diabetes duration and insulin use were consistently associated with remission." (PMID 41231326, 2025). "Diabetes mellitus (DM) is a chronic metabolic disease characterised by persistent hyperglycaemia due to impaired insulin secretion, insulin action or both." (PMID 40894207, 2025). "Diabetes mellitus (DM) is a complex metabolic disorder characterized by impaired insulin secretion and/or action, leading to chronic hyperglycemia." (PMID 40731875, 2025). "Diabetes mellitus (DM) is a chronic disease characterized by impaired insulin secretion, insulin resistance or both which leads to a host of devastating complications." (PMID 40129674, 2025). "In a retrospective cohort study involving 315 adult patients with uncontrolled diabetes, pharmacist-led interventions resulted in significant reductions in A1C levels and hypoglycemia incidents compared to physician-led interventions, particularly among patients treated with insulin." (PMID 40560023, 2025). "LSD1 inhibition can promote the differentiation of human embryonic stem cells to insulin-producing cells through ERK (extracellular regulated protein kinase) signaling, and improve the sensitivity of adipocytes to insulin, which may be a new strategy to improve obesity and treat diabetes." (PMID 40028036, 2025).
diabetes (continued). "At the same time, with the promotion of healthy lifestyle behaviors, diabetes management—particularly for T1D—has long benefited significantly from technological innovation applied in clinical settings, especially with regard to glucose self-monitoring and insulin delivery." (PMID 40870448, 2025). "In model 1, the use of exogenous insulin (ukb-b-7350) had a significant effect on OA (P < .05), and it could be determined that the use of exogenous insulin (ukb-b-7350) affected OA through diabetes (ebi-a-GCST90013891), which formed a partial mediating effect model." (PMID 41398760, 2025). "Diabetes mellitus (DM) is a widespread condition that involves abnormalities in the metabolism of glucose and insulin." (PMID 40771269, 2025). "Since insulin is often prescribed to patients with more advanced or poorly controlled diabetes, their higher cardiovascular risk may reflect underlying disease severity rather than a direct effect of insulin." (PMID 40836299, 2025). "However, in a well-designed, blinded RCT, both intervention and control groups follow the same standardised diabetes management protocols and, consequently, any differences observed in outcomes such as HbA1c, or insulin dose are more likely attributable to the immunomodulatory intervention itself." (PMID 40598585, 2025). "Diabetes mellitus (DM) is a chronic metabolic disease condition, affecting millions globally, characterized by hyperglycemia resulting from defects in insulin secretion, insulin resistance, or both." (PMID 40539164, 2025). "We hypothesise that BTG integration within structured telehealth support will enhance glycemic control, reduce diabetes-related emotional distress, and improve the efficiency of remote insulin titration processes, ultimately optimizing patient care delivery and healthcare resource utilisation." (PMID 41476921, 2025). "Furthermore, IQGAP1’s role in cellular metabolism and energy balance suggests its potential as a target for metabolic disorders, such as obesity and diabetes, where its involvement in signaling pathways related to insulin resistance and cell survival is critical." (PMID 41035668, 2025). "Type 1 diabetes mellitus (T1DM), known as insulin-dependent diabetes mellitus, is characterized by persistent hyperglycemia resulting from damage to the pancreatic β cells and an absolute deficiency of insulin, leading to multi-organ involvement and a poor prognosis." (PMID 39792010, 2025). "Diabetes mellitus (DM) is a cluster of chronic disorders characterized by persistent hyperglycemia resulting from impaired insulin secretion (type 1 diabetes [T1D]) and/or insulin resistance (type 2 diabetes [T2D])." (PMID 41334449, 2025). "Diabetes mellitus (DM) is a metabolic disorder that is shown by raised glucose levels (hyperglycemia) in the blood due to defective production of insulin and its action." (PMID 40735405, 2025). "Finally, only 52% of the participants were aware that patients with diabetes traveling to the West region may need to decrease their insulin dose." (PMID 40901237, 2025). "Reflecting the current literature, our research highlights the crucial role of insulin sensitivity in cognitive health, suggesting that eGDR may serve as a significant marker for assessing cognitive risk in individuals without diabetes." (PMID 40538401, 2025). "Furthermore, PA may confer multiple benefits to patients with diabetes or prediabetes, including improved insulin sensitivity, improved glycemic control, and improved cardiovascular health." (PMID 40630407, 2025). "Diabetes mellitus (DM) is a set of metabolic disorders marked by chronic hyperglycemia resulting from impaired insulin action and/or secretion." (PMID 41017587, 2025). "In contrast, insulin therapy was linked to lower remission rates, which may reflect the severity of diabetes at diagnosis rather than a direct effect of the medication." (PMID 41303028, 2025).
diabetes (continued). "Diabetes is a widespread chronic condition affecting metabolism, notable for chronic high blood sugar levels and disrupted processing of carbs, fats, and proteins, due to a deficiency in insulin production, a decrease in insulin effectiveness, or both." (PMID 40989163, 2025). "Our findings suggest that intensive SAIDEs exert synergistic effects of diet and exercise interventions by reducing inflammation, blocking oxidative stress, and enhancing insulin sensitivity, which may serve as potential mechanisms for delaying the onset of diabetes." (PMID 40225331, 2025). "Diabetes mellitus (DM) is a metabolic disorder characterized by inadequate insulin secretion or insulin resistance." (PMID 41000247, 2025). "Therefore, disruptions in these cellular components could contribute to beta-cell dysfunction and impaired insulin secretion, which are key features of diabetes pathophysiology." (PMID 40806765, 2025). "The heterogeneity observed in this analysis, as indicated by the I2 statistic, suggests high variability among the studies included, which may stem from several sources, such as differences in age, BMI, diabetes status, and metabolic health can influence postprandial glucose and insulin levels." (PMID 40507211, 2025). "Furthermore, metabolites derived from the gut microbiota can have dual effects on diabetes; short-chain fatty acids (e.g., acetate, propionate, and butyrate) are known to enhance insulin sensitivity, whereas endotoxins such as lipopolysaccharides induce inflammation and aggravate insulin resistance." (PMID 40647186, 2025). "A female patient from India was diagnosed with diabetes at 16 years of age and presented to a tertiary care diabetes clinic nine months later with hyperglycemia and dyslipidemia (hypercholesterolemia and hypertriglyceridemia), while on insulin and statin therapy." (PMID 40612841, 2025). "In addition to the well-known respiratory damage, many current studies have confirmed that PM2.5 can also cause damage to other multiple organs and systems, such as accelerated skin aging and increased insulin resistance, leading to diabetes and cardiometabolic diseases." (PMID 40149519, 2025). "However, studies included in our review delved deeper and revealed that acceptance of insulin by PwT2D may also be related to their perception and acceptance of their diabetes severity." (PMID 40171977, 2025). "Diabetes mellitus (DM) is a common metabolic disease marked by resistance to insulin or ineffective synthesis of insulin, which results in noticeably high blood glucose levels." (PMID 40063647, 2025). "Diabetes mellitus (DM) is a complex metabolic disorder characterized by chronic hyperglycemia resulting from impaired insulin secretion, insulin resistance, or both." (PMID 41382274, 2025). "These demographic differences could contribute to variations in glycemic response, as older adults with diabetes may have impaired insulin sensitivity or pancreatic function, resulting in more pronounced differences when comparing glycemic responses to different types of sugars." (PMID 40507211, 2025). "Suboptimal T1D management during adolescence may be attributed to several factors, including the transition from parent/caregiver management of T1D to self-management, increased insulin resistance resulting from hormonal changes, and psychosocial factors, including diabetes distress." (PMID 40303942, 2025). "Managing HD in individuals with diabetes can be especially complex, as these patients may experience significant blood glucose fluctuations due to interactions between dialysis, insulin dynamics, and counter-regulatory hormones, potentially leading to both hypoglycemia and hyperglycemia." (PMID 41009460, 2025). "People of all ages are increasingly affected by diabetes mellitus (DM) due to insufficient insulin action and secretion." (PMID 41007838, 2025).
diabetes (continued). "According to the SHAP values, the nine features that most contributed to diagnosing diabetes were glycohemoglobin (0.086), glucose (0.045), fasting glucose (0.039), age (0.023), cholesterol (0.011), osmolality (0.009), BMI (0.007), blood urea nitrogen (0.006), and insulin (0.005)." (PMID 40313792, 2025). "Additionally, the results demonstrated that insulin with olive leaves extract and ginger rhizome extract each alone significantly reduced creatinine levels in alloxan-induced diabetic type 1 Wistar rats compared to the combinations with/without insulin one week of treatment." (PMID 40365185, 2025). "Diabetes mellitus (DM) is a chronic metabolic disease characterised by persistent high blood glucose levels due to defects in cellular insulin function, secretion, or both in specific tissues." (PMID 41149529, 2025). "Additionally, some studies described self‐efficacy, fatalism, self‐identity and the concept of being sick, as well as the negative association of insulin with severe diabetes and the perception of insulin as the last resort." (PMID 40171977, 2025). "This, combined with sub-optimal nutrition in economically constrained individuals, especially during their first hospital visit for diabetes, may lead to unfavorable outcomes when implementing intensive insulin therapy for diabetic ketoacidosis, mimicking re-feeding syndrome." (PMID 39847589, 2025). "Diabetes mellitus (DM) is a chronic metabolic disease characterized by elevated blood glucose levels and inadequate insulin secretion." (PMID 40625625, 2025). "In animal studies, the mechanism is not clear, although results suggest that DDT may cause diabetes through mitochondrial dysfunction or insulin secretion defects." (PMID 41488239, 2025). "Finally, the possible additional benefits in terms of delayed insulin initiation, cardiorenal protection, and overall prevention of diabetes complications remain speculative and yet to be demonstrated." (PMID 39903441, 2025). "Diabetes mellitus (DM), one of the most common endocrine disorders and is characterized by hyperglycemia, with manifestations of insulin secretion defects and insulin resistance." (PMID 40584408, 2025). "It is also unclear whether insulin secretagogues can be used effectively in lean diabetes." (PMID 40995598, 2025). "Importantly, GK‐AAV8‐SCAMP5 rats demonstrated higher plasma insulin levels, improved glucose tolerance, and progressively decreased blood glucose levels compared to GK‐vehicle rats, suggesting the remission of diabetes." (PMID 40953307, 2025). "For instance, while thiazolidinediones consistently improved insulin sensitivity in obese cats, it is unknown if this effect would be sufficient to overcome the complex pathophysiology of a cat with long-standing clinical diabetes." (PMID 40941356, 2025). "Additionally, AST may amplify the benefits of exercise on insulin sensitivity and glucose metabolism, potentially leading to improved outcomes for individuals with diabetes." (PMID 40585493, 2025). "Thus, kisspeptin indirectly via adiponectin may have pleiotropic effects on metabolism by increasing glucose uptake and utilization in health and diabetes, insulin sensitivity, fatty acids oxidation, decreasing fat storage, and reducing inflammation." (PMID 40650041, 2025). "For example, a middle-aged adult patient with diabetes who visits a public health center for an insulin prescription may have their Hemoglobin A1C checked every three months, but would only undergo rapid sputum testing or chest imaging if a persistent cough raises clinical concern for tuberculosis." (PMID 40598462, 2025). "Diabetes mellitus (DM) is a chronic ailment stemming from absolute or relative insufficiency in insulin secretion and utilization disorders, which is typified by hyperglycemia." (PMID 41384020, 2025).
diabetes (continued). "In the present study we hypothesized that hypomagnesemia in patients without known diabetes would be associated with lower insulin sensitivity and impaired insulin response to an oral glucose tolerance test (OGTT) 1 year after kidney transplantation." (PMID 39911868, 2025). "Diabetes mellitus (DM) is a metabolic, endocrine disease affecting 25% of the world population, characterized by elevated blood glucose levels either due to limited insulin synthesis or impaired body response to insulin." (PMID 40761498, 2025). "Thus, ghrelin and leptin, along with insulin, may be interrelated in diabetes-induced changes in food intake and independent alterations in ghrelin levels." (PMID 41195415, 2025). "A prominent example of that is the nanogel designed to deliver insulin for diabetes treatment might include pH-sensitive components that release insulin only when encountering the acidic environment inside endosomes, preventing premature degradation of insulin and ensuring its efficacy." (PMID 39861715, 2025). "Moreover, the findings suggest that DA-9701 may also have a beneficial impact on insulin secretion, potentially offering dual therapeutic action in diabetes management." (PMID 40577398, 2025). "These preliminary findings provide concept-level evidence that B. longum CKD1 may represent a safe and effective therapeutic option, either as a noninvasive monotherapy or as an adjunct to conventional insulin therapy, for managing diabetes mellitus in companion animals." (PMID 41472082, 2025). "Diabetes mellitus (DM) is a serious metabolic disorder characterized by elevated blood glucose levels resulting from insufficient insulin production, impaired insulin action on target tissues, or a combination of both." (PMID 40687580, 2025). "Type 1 diabetes mellitus (T1D or T1DM) is a chronic autoimmune disease caused by the immune-mediated destruction of insulin-producing pancreatic beta cells, resulting in the progressive loss of endogenous insulin secretion, hyperglycemia, and a lifelong need for exogenous insulin." (PMID 40004833, 2025). "Thus, the level of threshold should be used to detect high or very high glucose levels, but not usual post-meal glucose levels, since this could lead to alert after each meal, which can increase diabetes burdens, or can lead to overcorrection of insulin." (PMID 40671052, 2025). "Diabetes mellitus (DM), which includes T2D, is a complex metabolic disorder of multifactorial origin with impaired insulin secretion or sensitivity with raised blood glucose levels." (PMID 41303853, 2025). "Additionally, rutin exerts therapeutic benefits in diabetes management by reducing intestinal carbohydrate absorption, stimulating insulin secretion from pancreatic β-cells, preventing degeneration of Langerhans islets, enhancing tissue glucose uptake, and suppressing hepatic gluconeogenesis." (PMID 40395731, 2025). "This pattern is sometimes classified as part of “brittle diabetes” (the term “brittle diabetes” refers to a form of type 1 diabetes characterized by severe glycemic variability and recurrent episodes of hypoglycemia or ketoacidosis despite intensive insulin therapy)." (PMID 41149081, 2025). "Diabetes mellitus (DM) is a chronic metabolic disorder characterized by persistent hyperglycemia resulting from impaired insulin secretion or action." (PMID 41304842, 2025). "Diabetes mellitus (DM) is a chronic metabolic disorder that significantly disrupts insulin secretion and action, leading to various complications." (PMID 41536404, 2025). "Additionally, we found that SHBG levels were positively correlated with HDL and apoA and negatively correlated with triglycerides, hypercholesterolemia, fasting insulin, fasting glucose, diabetes, glycated hemoglobin, obesity, BMI, waist circumference, and waist‐to‐hip ratio." (PMID 41427029, 2025).